METTL3 (methyltransferase 3, N6-adenosine-methyltransferase complex catalytic subunit)
Diseases named in the same sentence as METTL3 in open-access papers (continued):
Sharing a sentence is not in itself a finding about the gene and the disease.
hepatocellular carcinoma (continued). "Upregulation of methyltransferase-like 3 (METTL3), the catalytic core of the m6A methyltransferase complex, increases m6A levels and results in significant effects on the progression of hepatocellular carcinoma (HCC)." (PMID 35456475, 2022). "Our study demonstrated that METTL14 favours migration and invasion of CM cells, which is not contradictory to the activity of METTL3; for example, METTL3 and METTL14 can play opposing roles in the regulation of hepatocellular carcinoma." (PMID 36264762, 2022). "Reduced METTL3 in hepatocellular carcinoma (HCC) results in increased infiltration of DCs in the TIME, which leads to the overall upregulation of major histocompatibility complex (MHC) molecules, costimulatory molecules, and adhesion molecules and is closely related to the prognoses of HCC." (PMID 36225914, 2022). "Moreover, it was found that combined levels of METTL3 and YTHDF1 could reflect the malignancy state and prognosis of hepatocellular carcinoma (HCC)." (PMID 33816266, 2021). "For instance, METTL3-mediated m6A modification led to LINC00958 upregulation through stabilizing its RNA transcript, and LINC00968 sponged miR-3619-5p to upregulate HDGF expression thereby facilitating the lipogenesis and progression of hepatocellular carcinoma (HCC)." (PMID 32982586, 2020).
breast cancer (212 papers, 2017 to 2026). A primary or metastatic malignant neoplasm involving the breast. "Conversely, in breast cancer, increased METTL3‐mediated m6A methylation has been associated with enhanced tumorigenicity, potentially through modulating the stability and translation of genes involved in cell cycle progression and metastasis." (PMID 40919129, 2025). "METTL3 is widely recognized as a proto-oncogene, and elevated m6A levels in peripheral blood have been proposed as a potential diagnostic biomarker for breast cancer." (PMID 40918643, 2025). "Elevated expression levels of METTL3 have been found to contribute to tumor development by promoting adenylate kinase-4 expression in breast cancer while causing tamoxifen treatment resistance." (PMID 39033180, 2024). "In summary, our study provides further insight into the function of METTL3 and m6A in breast cancer by regulating tumor-associated AS switches." (PMID 36725888, 2023). "Kaplan–Meier survival analysis revealed that high METTL3 protein expression was significantly associated with poor prognosis in invasive ductal carcinoma and luminal breast cancer tissues." (PMID 36609396, 2023). "For instance, studies on METTL3 have revealed that it is overexpressed in breast cancer compared to normal mammary tissues, and its silencing in different breast cancer cell lines has been associated with increased apoptosis and decreased proliferation." (PMID 36725888, 2023). "A breast cancer study showed that depletion of METTL3 causes exons of specific genes to be retained." (PMID 37675218, 2023). "Our data further demonstrated that METTL3 regulates tumor-associated AS switches in breast cancer, and that METTL3 depletion causes mainly alternative first and exon skipping events." (PMID 36725888, 2023). "We characterize for the first time the role of METTL3 in modulating breast cancer-associated AS programs, expanding the role of the m6A-methyltransferase in tumorigenesis." (PMID 36725888, 2023). "Starting with the m6A writer, METTL3 has been found upregulated in late stages of breast cancer and associated with worse prognosis." (PMID 37369946, 2023). "We describe that METTL3 regulates breast cancer-associated AS switches through a direct mechanism involving m6A deposition at the proximity of splice sites." (PMID 36725888, 2023). "In conclusion, our study has illustrated the critical role of METTL3-mediated m6A modification in PD-L1 mRNA stabilization in an IGF2BP3-associated manner in breast cancer cells." (PMID 35197058, 2022). "Loss of ADAR1 inhibits breast cancer growth and decreases METTL3 and ARHGAP5 expression levels in vivo." (PMID 36077054, 2022). "After evaluating the respective staining intensity scores, we found that, indeed, the PD-L1 expression in breast cancer was positively associated with the expression of METTL3 or IGF2BP3." (PMID 35197058, 2022). "The numerous genetic mutations present in breast cancers and the various molecular subtypes warrants a more in-depth analysis of the role of METTL3 and m6A in breast cancer." (PMID 36008936, 2022). "METTL3 expression was found to be upregulated in lung cancer, breast cancer, liver cancer and glioblastoma and associated with metastasis in lung cancer and oral squamous cell carcinoma." (PMID 34094960, 2021). "METTL3 can promote apoptosis in gastric and breast cancer cells and is associated with ubiquitin-dependent process in pancreatic cancer cells." (PMID 32547941, 2020). "Likewise, increased METTL3 levels were linked to greater proliferation, suggesting that specific breast cancer cases with elevated METTL3 expression tend to proliferate more." (PMID 40918643, 2025). "This epigenetic mark exhibits a context-dependent duality: while high levels of METTL3-mediated methylation promote cell proliferation and metastasis and inhibit apoptosis in breast cancer (BC), they are also implicated in non-small cell (NSCLC) and small-cell (SCLC) lung cancers." (PMID 41157107, 2025).
breast cancer (continued). "Additionally, METTL3 can regulate oncogenesis-related AS events in breast cancer, five of which are associated with poor prognosis." (PMID 38405130, 2024). "However, our study aimed at investigating the detailed specific molecular mechanisms underlying PD-L1 m6A modification and the impact of METTL3 on immunoregulation in breast cancer." (PMID 35197058, 2022). "However, some bioinformatics analysis showed that METTL3 was decreased in the breast cancer tissues and associated with better survival." (PMID 33431790, 2021). "The opposite result was also reported such that the deficiency of METTL3 could inhibit the proliferation of breast cancer cell line MCF-7, by m6A-level-decreasing-mediated Bcl-2 up-regulation." (PMID 32766145, 2020). "Additionally, loss of ADAR1 inhibits breast cancer growth and decreases METTL3 and ARHGAP5 in vivo." (PMID 36077054, 2022). "However, the biological function of circRNAs derived from METTL3 in breast cancer and the underlying molecular mechanism remains unclear." (PMID 33867838, 2021). "The only studies of breast cancer have shown that METTL3-mediated enhancement of m6A level could promote the proliferation of breast cancer cells, while the high level of m6A caused by FTO knockdown could inhibit the proliferation and metastasis of breast cancer." (PMID 32766145, 2020). "We then analyzed the protein levels of METTL3 in pan-cancer via the UALCAN database and showed that METTL3 protein expression levels were up-regulated in different types of cancers, including breast cancer, ovarian cancer, and LUAD." (PMID 41362669, 2026). "J. OH33 reported that the decreased METTL3 expression leads to reduced SRSF11 expression in breast cancer (BRCA), Colon adenocarcinoma (COAD), lung adenocarcinoma (LUAD), and stomach adenocarcinomas (STAD)." (PMID 41584036, 2026). "For instance, ZNF217 was reported to reduce mRNA m6A methylation in embryonic stem cells and breast cancer cells by sequestering the m6A 'writer' METTL3, thereby supporting embryonic stem cell pluripotency and promoting breast cancer progression 40-43." (PMID 40093906, 2025). "METTL3 acetylation has been found to abrogate its nuclear translocation and impair breast cancer cell migration and invasion." (PMID 40651967, 2025). "In recent years, a wealth of studies have unequivocally demonstrated that the methyltransferase METTL3 assumes a pivotal role in the pathogenesis of breast cancer." (PMID 39972939, 2025). "In breast cancer cells, endoplasmic reticulum (ER) stress induces XBP1s-dependent transcriptional activation of METTL3/METTL14, thereby elevating cellular m6A levels." (PMID 41164187, 2025). "Prior studies have only examined METTL3’s broad function in RNA methylation and its relevance in different cancers, such as lung and breast cancer." (PMID 40177651, 2025). "Our qPCR data demonstrate that knockdown of EGR1 significantly reduces METTL3 expression while upregulating LINC01133 levels in ER+ breast cancer cells." (PMID 40641925, 2025). "On the other hand, METTL3 controls PD-L1 expression on breast cancer favoring the antitumor activity of the immune cells." (PMID 41339932, 2025). "For example, in breast cancer, METTL3-mediated methylation exhibits contrary roles: it can function as a tumor suppressor in some contexts while acting as an oncogenic encourager by maintaining tumor cell stemness in others." (PMID 41157107, 2025). "We further investigated the potential roles of the METTL3/SLC7A11 axis in vivo breast cancer progression." (PMID 39800682, 2025). "For instance, the METTL3/IGF2BP3 axis-mediated stabilization of PD-L1 mRNA suppresses anti-tumor immunity in breast cancer." (PMID 40279954, 2025). "In the breast cancer immune microenvironment, PD-L1 functions as a direct target of METTL3-regulated m6A epigenetic modification." (PMID 40986143, 2025).
breast cancer (continued). "METTL3 emerges as a clinically validated prognostic and immunoregulatory biomarker in breast cancer, whereas METTL14 is correlated with both survival outcomes and tumor-infiltrating lymphocyte dynamics in rectal adenocarcinoma." (PMID 40986143, 2025). "In breast cancer, methyltransferase like 3 (METTL3), an m6A methyltransferase, accelerates pri-miR-221-3p maturation in an m6A-dependent manner, leading to adriamycin resistance in MCF-7 cells." (PMID 41369385, 2025). "In research on breast cancer, BBR treatment blocked breast cancer cell growth and metastasis partly by regulating METTL3-mediated m6A modification of FGF7 mRNA." (PMID 40829428, 2025). "Recently, a METTL3 inhibitor demonstrated promising preclinical results in several cancer types, yet the therapeutic potential of targeting m6A in breast cancer (BCa) remains poorly understood." (PMID 41310336, 2025). "Acetylation of METTL3 impedes its nuclear translocation, suppressing the metastasis of breast cancer." (PMID 40651967, 2025). "Knockdown of METTL3 inhibited Pin1-induced clonal expansion of the breast cancer MCF7 cells, but promoted the growth of 4T1 tumors in vivo." (PMID 40786181, 2025). "In breast cancer, METTL3-mediated m6A modification is regulated by ADAR1, which subsequently promotes breast cancer progression." (PMID 40406121, 2025). "In breast cancer (BC), METTL3 knockdown significantly increases chemosensitivity to doxorubicin via modulation of the EGF/RAD51 signaling axis." (PMID 40406121, 2025). "METTL3 promotes aberrant expression of mammalian hepatitis B X‐interacting proteins driving breast cancer aggressiveness." (PMID 39006762, 2024). "Previous studies have demonstrated that METTL3 has an important role in the ceRNA network of breast cancer." (PMID 38429907, 2024). "For example, in breast cancer, METTL3-mediated activation of PD-L1 mRNA is IGF2BP3-dependent, the METTL3/IGF2BP3 axis upregulates the m6A modification of PD-L1 mRNA, further increasing the stability of PD-L1 mRNA and inhibiting tumor immune surveillance." (PMID 38762484, 2024). "In pulmonary metastases of breast cancer cells, it was found that METTL3 expression is increased while FTO expression is decreased." (PMID 39192357, 2024). "It has been demonstrated that the miR-577/POSTN axis controls the downstream ILK/AKT/mTOR signaling pathway through the METTL3-mediated overexpression of lnc00520 to accelerate the development of breast cancer." (PMID 38339157, 2024). "In breast cancer, high expression of METTL3 and IGF2BP3 maintains PD-L1 mRNA stability, promotes T cell senescence, and evades immune surveillance." (PMID 39033180, 2024). "An acetylation‐mimetic METTL3 variant disrupts this process, leading to diminished metastatic capacity, suggesting that METTL3's acetylation state is pivotal in modulating its oncogenic potential in breast cancer." (PMID 39377984, 2024). "In bladder and breast cancer, METTL3 mediates PD-L1 mRNA m6A modification and upregulates its expression through IGF2BP3-dependent manner, resulting the exhaustion of T-cells and the suppression of T cell activation and infiltration." (PMID 38322265, 2024). "METTL3 promotes breast cancer (BC) promotion and accelerates apoptosis by targeting the apoptosis inhibitor B-cell lymphoma-2 (Bcl-2)." (PMID 38711100, 2024). "In breast cancer, METTL3 expression increased PD-L1 stability and expression, and METTL3/IGF2BP3 knockdown significantly enhanced the immune response." (PMID 39033180, 2024). "In breast cancer, the METTL3-METTL14 complex upregulates the expression of genes like Bcl-2 and CXCR4 through m6A-dependent mechanisms, thereby fostering breast cancer growth and metastasis." (PMID 38965238, 2024). "Our previous study has found that METTL3 knockdown in a breast cancer mouse model enhanced PD-1 immunotherapy efficacy by improving CD8+ T cell infiltration and reducing immunosuppressive cells, thereby promoting an anti-tumor immune environment." (PMID 39720723, 2024).
breast cancer (continued). "For example, METTL3, VIRMA, FTO, and IGF2BP1 aberrant expression linked to breast cancer, METTL3, FTO, and YTHDF1 disrupted expression promotes lung cancer, and METTL3/14, FTO, and YTHDF2 dysregulated expression promotes acute myeloid leukemia." (PMID 38544837, 2024). "Downregulation of METTL3 has been reported in HR + HER2‐ breast cancer, promoting resistance to doxorubicin, paclitaxel, and cisplatin." (PMID 38545841, 2024). "To assess the functional impact of METTL3 in breast cancer, we next performed GO analysis of the DEG and the DSE of METTL3 knockdown in MCF10-A, MCF7 and MDA-MB-231 cell lines." (PMID 36725888, 2023). "HBXIP prevents miRNA let-7 g, which acts as a negative regulator of METTL3, from inhibiting METTL3, thus maintaining its expression and accelerating cell proliferation and metastasis in breast cancer." (PMID 38260844, 2023). "In breast cancer, excessive METTL3 resisted cell apoptosis as well as exhibited Adriamycin resistance." (PMID 36162823, 2023). "High levels of YAP/TAZ were found in the nucleus of breast cancer cells after inducing the expression of METTL3, while deleting the expression of YTHDF2 corrected such deviated expression in the nuclears." (PMID 36609396, 2023). "METTL3 knockdown cells exhibited a significant defect in proliferation, which was accentuated in the breast cancer cell lines MCF7 and MDA-MB-231 compared to METTL3 knockdowns in MCF10-A." (PMID 36725888, 2023). "Knocking down Mettl3 at different stages of breast cancer progression indeed shows unique effects at each stage." (PMID 38023205, 2023). "To investigate the expression of METTL3 in breast cancer, we examined its protein levels in breast cancer tissues and paired adjacent normal tissues." (PMID 36609396, 2023). "And miR-221-3p inhibition was confirmed to negate the METTL3-induced breast cancer cell resistance to doxorubicin." (PMID 37264402, 2023). "In breast cancer, METTL3 accelerates miR-221-3p precursor maturation, induces MDR1 and BCRP expression via the miR-221-3p/HIPK2/Che-1 axis, then promotes adriamycin resistance in cancer cells." (PMID 37996892, 2023). "Here, we identify genome-wide METTL3-regulated AS events in breast cancer cell lines, and reveal both direct and indirect connections between m6A and AS." (PMID 36725888, 2023). "The positive feedback loop of HBXIP/let-7g/METTL3/HBXIP was proposed to accelerate proliferation of breast cancer cells and then aggravate the process of HCC." (PMID 36970605, 2023). "We obtained breast cancer patient tumor tissues and found that METTL3 was upregulated in tumor samples." (PMID 37589705, 2023). "METTL3 was found to be upregulated in breast cancer tissues and cells, where it promoted 6mA modification of the 3′ UTR of B-cell/lymphoma 2 (BCL-2) mRNA." (PMID 36673448, 2023). "Depletion of METTL3 reduced m6A levels, and resulted in proliferation defects and increased apoptosis, suggesting that METTL3 functions as an oncogene in breast cancer." (PMID 36725888, 2023). "Specifically, IGF2BP3 was reported to be associated with PD-L1 and promote stabilization of PD-L1 mRNA by METTL3-mediated m6A modification in breast cancer." (PMID 38171932, 2023). "METTL3 was reported as a potential upstream m6A methyltransferase of PD-L1, thereby regulating PD-L1 expression and stability in breast cancer cells." (PMID 39872957, 2023). "Similar to METTL3-dependent AS switches, m6A deposition was also prominent in categories important for breast cancer progression and metastasis." (PMID 36725888, 2023). "Using the MCF10 model of breast cancer, we reduced m6A levels by targeting METTL3, the main cellular m6A RNA methyltransferase." (PMID 38023205, 2023). "In a breast cancer lung metastasis model, upregulated METTL3 methylates KRT7-AS to enhance its expression, which then forms duplex with KRT7 mRNA to increase its stability and expression through recruitment of the IGF2BP1/HuR complex." (PMID 37369946, 2023).